LAG3 (lymphocyte activating 3)
Diseases named in the same sentence as LAG3 in open-access papers (continued):
Sharing a sentence is not in itself a finding about the gene and the disease.
metastatic melanoma (continued). "In this study, we investigated baseline LAG-3 expression in metastatic melanoma specimens from patients treated with combination anti-LAG-3 + anti-PD-1 immunotherapy." (PMID 37808404, 2023). "A subsequent study found that metastatic melanoma patients who responded to anti-LAG-3 and anti-PD-1 combination therapy had higher baseline TCR clonality with CD8+LAG-3+ clones that expanded and shifted to a more cytotoxic phenotype resembling NK cells." (PMID 37900283, 2023). "The blockade of additional immune checkpoints, especially TIGIT and LAG-3, has been extensively explored, but so far only a LAG-3 antibody has been approved for combination with nivolumab to treat unresectable or metastatic melanoma." (PMID 37332070, 2023). "More importantly, a recent study assessing the therapeutic implication of ipilimumab, a CTLA-4 antibody, showed that ipilimumab increased the frequency of LAG-3 expression on tumor-infiltrating cells in metastatic melanoma patients." (PMID 37509517, 2023). "The anti-lymphocyte activation gene 3 (LAG-3) antibody, relatlimab, has been approved in combination with nivolumab for untreated metastatic melanoma." (PMID 37509394, 2023). "Recently another treatment combination targeting Lymphocyte-activation gene 3 (LAG-3) and PD-1 has been approved for the treatment of metastatic melanoma." (PMID 37046745, 2023). "This study sought to evaluate the association between baseline LAG-3 expression and clinical outcomes following anti-LAG-3 and anti-PD-1-based immunotherapy in metastatic melanoma." (PMID 37808404, 2023). "Relatlimab plus nivolumab (anti–LAG-3+anti–PD-1) combination therapy has shown a progression-free survival benefit over anti–PD-1 monotherapy as a first-line treatment for patients with metastatic melanoma and has now been approved by the FDA." (PMID 36719749, 2023). "In the blood of patients with metastatic melanoma treated with relatlimab (anti-LAG-3) and nivolumab (anti-PD-1) the “adaptive” NK cell subset exhibited the highest LAG-3 expression, and responding patient NK cells were activated with treatment." (PMID 38090565, 2023). "Relatlimab, a LAG-3-directed monoclonal antibody, is the first LAG-3 inhibitor approved in combination with nivolumab by the FDA for the treatment of previously untreated unresectable or metastatic melanoma based on the results of the RELATIVITY-047 trial." (PMID 37509517, 2023). "For example, the recent approval of relatlimab for the treatment of metastatic melanoma as a first-in-class drug targeting LAG3 opens the door for trials with EBVaGC, which are readily justified by the high expression of LAG3 in EBVaGC." (PMID 36680216, 2023). "A new ICB relatlimab-rmbw (lymphocyte activation gene-3 (LAG-3)-directed mAb) was approved by the FDA in combination with nivolumab for unresectable or metastatic melanoma on March 18, 2022." (PMID 36209184, 2022). "Since the completion of this clinical trial, PD-1 inhibitors, either as single agents or in combination with a CTLA-4 or a LAG-3 inhibitor, have replaced ipilimumab monotherapy as the standard of care for metastatic melanoma." (PMID 36089578, 2022). "These checkpoints thus represent attractive therapeutic targets, and indeed the LAG3 inhibitor relatlimab was recently approved for the treatment of metastatic melanoma in combination with anti-PD-1 therapy." (PMID 36313654, 2022). "In accordance, recent studies demonstrated strong and durable anti-tumor immune responses in patients receiving the anti-LAG3 monoclonal antibody Relatlimab for metastatic melanoma." (PMID 35406483, 2022). "New immunotherapy combinations: A new study, RELATIVITY-047, suggested using combined immunotherapy for unresectable or metastatic melanoma with anti-PD-1 and anti-lymphocyte-activation gene 3 (LAG-3) as active agents." (PMID 36232957, 2022). "Relatlimab, an anti-LAG3 antibody with promising results in metastatic melanoma, is under investigation in combination with nivolumab (NCT02996110)." (PMID 34885091, 2021).
metastatic melanoma (continued). "Second, due to the promising result of IMP321 in metastatic melanoma, the use of anti-LAG3 mAbs in metastatic tumors requires further study." (PMID 35111155, 2021). "We further tested LAG3 methylation as a predictive biomarker for disease progression in metastatic melanoma patients with ICB (N = 118)." (PMID 32861198, 2020). "To further test the predictive significance of LAG3 methylation, we analyzed tumor tissue obtained from metastatic melanoma patients treated with ICB with regard to progression under therapy." (PMID 32861198, 2020). "In metastatic melanoma, PD-1, p = 1.48e−148, Pearson’s rho = 0.917; LAG3, p = 4.28e−163, Pearson’s rho = 0.931; IDO1, p = 2.38e−53, Pearson’s rho = 0.690)." (PMID 29515971, 2018). "Finally, the authors performed high‐dimensional flow cytometry in peripheral blood mononuclear cells (PBMC) from a large cohort of metastatic melanoma patients that received anti‐PD1 + anti‐LAG3." (PMID 40517319, 2025). "In 2022, the FDA approved the LAG-3 inhibitor, Relatlimab, in combination with nivolumab for the treatment of unresectable or metastatic melanoma in adults and children aged 12 or older, making LAG-3 the third immune checkpoint to be applied in clinical settings after PD-1 and CTLA-4." (PMID 40012016, 2025). "Several anti-LAG-3 mAbs are currently undergoing clinical trials, and the combination of relatlimab (anti-LAG-3) with nivolumab (anti-PD-1) has already been approved for treating unresectable or metastatic melanoma, based on results from the Phase II/III RELATIVITY-047 (NCT03470922)." (PMID 39684559, 2024). "Among these, LAG-3 became the third clinically validated checkpoint target, with the recent RELATIVITY-047 (NCT03470922) data resulting in FDA approval of the anti-LAG-3 antibody relatlimab in combination with the anti-PD-1 antibody nivolumab for the treatment of unresectable or metastatic melanoma." (PMID 37795090, 2023). "Therefore, the assessment of LAG-3 expression via IHC warrants further evaluation to determine its role as a predictive marker of response and survival in metastatic melanoma." (PMID 37808404, 2023). "For details, in 2022, the U.S. FDA approved the combination therapy of relatlimab and nivolumab for adults and children 12 years of age and older with unresectable or metastatic melanoma, setting the milestone for the application of LAG-3 inhibitors, as a novel ICI, in cancer treatment." (PMID 36765782, 2023). "We evaluated blood samples from 40 immunotherapy-naive or prior immunotherapy–refractory patients with metastatic melanoma treated with anti–LAG-3+anti–PD-1 in a phase I trial using single-cell RNA and T cell receptor sequencing (scRNA+TCRαβ-Seq) combined with other multiomics profiling." (PMID 36719749, 2023). "Recently, a new dual anti-PD-1 (Nivolumab) and anti-LAG-3 (Relatimab) treatment developed by Bristol Myers Squibb (Opdualag), was approved by the Food and Drug Administration (FDA) as the first LAG-3 blocking antibody combination for unresectable or metastatic melanoma." (PMID 35954196, 2022). "Here, treatment of metastatic melanoma with the anti-LAG3 antibody Relatlimab in combination with nivolumab has shown promising results in a phase II/III trial, which may result in FDA-approval." (PMID 35406483, 2022). "LAG3 is a coinhibitory receptor expressed on activated T cells and has now become part of the repertoire of combinatorial immunotherapeutics available for the treatment of metastatic melanoma." (PMID 36428720, 2022). "Interestingly, recent results of a phase 3 clinical trial in patients with metastatic melanoma showed that anti-LAG-3 antibody combined with anti-PD-1 improves overall survival in patients with metastatic melanoma, compared with anti-PD-1 monotherapy." (PMID 34771650, 2021).
metastatic melanoma (continued). "For example, high levels of CTLA-4, PD-1, PD-L1/2, LAG3, and IDO1 that we detected in metastatic melanoma, were many fold times more significantly associated with high cytolytic levels, pointing towards the existence of immunosuppression in these metastatic tumors." (PMID 29515971, 2018). "Finally, it would be intriguing to determine whether this LAG3hi immunotype is reflective of patients that will respond to anti‐PD1 + anti‐LAG3 in cancers beyond metastatic melanoma." (PMID 40517319, 2025). "Indeed, relatlimab, a first-in-class LAG3 inhibitor, was recently approved for the first-line treatment of metastatic melanoma in combination with the anti-PD-1 antibody nivolumab, improving progression-free survival and response rates compared to anti-PD-1 alone." (PMID 36313654, 2022). "The combination of the LAG3 inhibitor Relatlimab with Nivolumab is approved for treating metastatic melanoma, marking the debut of FDA-approved LAG3 monoclonal antibody combination therapy." (PMID 39839672, 2024). "With the recent approval of anti-LAG-3 for the treatment of late-stage metastatic melanoma, identification of biomarkers that can inform on prescription of monotherapy anti-PD-1, versus combinations that include anti-CTLA-4 and LAG-3, are urgently needed." (PMID 38217840, 2024). "Recently, the USFDA approved the combination of Nivolumab and the first lymphocyte-activation gene 3 (LAG-3)-blocking antibody, Relatlimab (BMS986016), as treatment for patients with unresectable or metastatic melanoma." (PMID 37251920, 2023). "Importantly, LAG-3 inhibition in combination with PD-1 inhibition offered impressive efficacy with modest increases in toxicity over single agent PD-1 inhibitor and has been U.S. Food and Drug Administration approved for the first-line therapy of patients with metastatic melanoma." (PMID 37484526, 2023). "Dual inhibition of LAG-3 and programmed cell death receptor-1 (PD-1) significantly improved progression-free survival (PFS) in metastatic melanoma patients compared to anti-PD-1 therapy alone." (PMID 37808404, 2023). "In 2022, relatlimab, which targets lymphocyte-activation gene 3 (LAG-3), was approved by the FDA for adult and pediatric use with metastatic melanoma." (PMID 36613491, 2022). "Lymphocyte-activation gene-3 (LAG-3, CD233) is referred to as a third IC, after the U.S. Food and Drug Administration approved the combination drug relatlimab/nivolumab (anti-LAG-3/anti-PD-1) for treatment of inoperable or metastatic melanoma in 2022." (PMID 41011055, 2025). "Thus far, >20 LAG-3-targeting therapeutics are under clinical trials, and a fixed-dose combination of anti-LAG-3 and anti-PD-1 has been approved for unresectable or metastatic melanoma treatment." (PMID 39507530, 2024). "The first anti-LAG3 human monoclonal antibody, Relatlimab (Bristol-Myers Squibb), has been recently approved (March 2022) by FDA in combination with Nivolumab for metastatic melanoma therapy and is currently under study in 46 randomized clinical trials in oncology." (PMID 38322766, 2024). "Monoclonal antibodies against CTLA-4 or PD-1 or PDL-1 are the most studied ICIs in randomized clinical trials, however, more recently, an anti-LAG3 (Lymphocyte activation gene-3) antibody, Relatlimab, has been approved by FDA in combination with Nivolumab for metastatic melanoma therapy." (PMID 38322766, 2024). "On the one hand, these boost antitumoral response by targeting membrane-bound LAG-3 in T cells, the most current example being the drug relatlimab, showing interesting effectivity when combined with an anti PD-1 agent in a phase III trial for metastatic melanoma." (PMID 38233492, 2024). "In addition, a fixed-dose combination of the LAG-3 blocking antibody relatlimab and the PD-1 blocking antibody nivolumab, known as opdualag (Bristol Myers Squibb) approved by the FDA, has shown a promising improvement in PFS for patients with unresectable or metastatic melanoma." (PMID 38032111, 2023).
colorectal cancer (64 papers, 2018 to 2026). A primary or metastatic malignant neoplasm that affects the colon or rectum. "A study in 773 patients with stage I-III colorectal cancer (CRC) patients indicated that high tumoral immune checkpoints (lymphocyte-activation gene 3) LAG-3 and PD-1 were associated with poor survival." (PMID 35392976, 2022). "Individual and combined high expression of TIM-3, LAG-3, and PD-1 on stromal immune cells are associated with better colorectal cancer prognosis." (PMID 35936516, 2022). "Head and neck squamous cell carcinoma (HNSCC) and colorectal carcinoma with LAG3-expressing TILs were associated with lymph node metastasis, larger tumor size and shorter overall survival in the case of nodal status-negative HNSCC." (PMID 32232506, 2020). "Moreover, increased expression of LAG-3 on CD8+ TILs was associated with better PFS in liver metastases colorectal cancer patients." (PMID 35804964, 2022). "The results suggest that individual and combined high expression of TIM‐3, LAG‐3, and PD‐1 on stromal immune cells are associated with better colorectal cancer prognosis, suggesting there is added value to investigating multiple immune checkpoints simultaneously." (PMID 33338327, 2021). "In murine models of colorectal cancer, dysbiosis has been associated with T cell exhaustion, characterized by an increased population of PD-1+LAG-3+TIM-3+ CD8+ T cells, suggesting that microbial imbalance may promote tumor progression through immune dysfunction." (PMID 41246357, 2025). "Studies have shown that when LAG3 antibody is used to treat tumor-bearing mice with colorectal cancer MC38 and fibrosarcoma Sa1N, tumor growth slightly decreases and the clearance rate is very limited." (PMID 40761795, 2025). "The high expression of immune exhaustion genes, including PD-L1, LAG3, and T-bet, in CD8+ T cells has been linked to reduced OS in colorectal cancer." (PMID 39901202, 2025). "In cancers such as melanoma, lung cancer, colorectal cancer, and pancreatic cancer, LAG-3 is overexpressed on tumor-infiltrating lymphocytes, contributing to immunosuppression and enabling tumor cells to evade immune attack." (PMID 40574024, 2025). "Studies have shown that LAG-3 is highly expressed in infiltrating T cells in various cancers, including colorectal cancer, NSCLC, pancreatic cancer, and head and neck cancer." (PMID 40574024, 2025). "Among these immune checkpoint genes, highly expressed CTLA4, LAG3 and TIGIT has been treated as diagnostic biomarkers for colorectal cancer." (PMID 37693891, 2023). "LAG3 (+) Treg cells were also found to suppress macrophages’ proinflammatory activation in colorectal cancer patients." (PMID 36575439, 2022). "Further studies are needed to establish the mechanisms of CTLA-4 and LAG3 in patients with colorectal cancer." (PMID 35434132, 2022). "In RAS wild-type colorectal cancer patients, cetuximab was shown to increase TILs together with PD-L1 and LAG3 upregulation." (PMID 36231138, 2022). "In stage II colorectal cancer, the expression of LAG-3 in TILs at the tumor front predicts better treatment outcomes in both the entire stage II and the subgroup of stage II microsatellite-stable tumors." (PMID 36077354, 2022). "In colorectal carcinoma, LAG3 was expressed at higher levels in microsatellite unstable compared with microsatellite stable tumors." (PMID 31434339, 2019). "Clinical trials based on LAG-3 inhibitors in the treatment of colorectal cancer." (PMID 41112277, 2025). "In colorectal carcinoma, patients high percentage of LAG‐3+ cells exhibit shorter survival period." (PMID 40091778, 2025). "In addition, LAG-3 mAb and PD-1 mAb have also been shown to have significant synergistic effects in colorectal cancer." (PMID 38177102, 2024). "Colorectal cancer patients presented an enrichment of circulating Treg cells, where the LAG-3+TIM-3+ subset exhibited stronger expression of inhibitory molecules, and LAG-3+TIM-3+ Treg cells could inhibit pro-inflammatory macrophage activation." (PMID 36077354, 2022).
colorectal cancer (continued). "High LAG-3 expression on tumor-infiltrating lymphocytes is positively associated with differentiation, lymph metastasis, invasion, tumor, node and metastasis (TNM) and Duke stage of colorectal cancer." (PMID 36077354, 2022). "Moreover, LAG-3+ Tregs from colorectal cancer patients are highly suppressive and proliferative." (PMID 35455287, 2022). "In colorectal cancer (CRC) patients (n = 30) receiving pembrolizumab combined with FOLFOX6, CR/PR patients had lower baseline levels of LAG3+PD-1+CD8+T cells, and patients below the median level of LAG3+PD-1+CD8+T cells exhibited better PFS." (PMID 41535994, 2026). "Specifically, in MSI colorectal cancers, immune ESTIMATE, HAVCR2 (TIM-3), CD274 (PD-L1), LAG3 (LAG-3), and PDCD1 (PD-1) each showed significant inverse correlations with GALNT7 expression across the three cohorts." (PMID 40824763, 2025). "Remarkably, the promoter methylation status of LAG3, TIGIT, and PD-L1 was anti-correlated with gene expression in colorectal cancer." (PMID 39064019, 2024). "The results showed that in colorectal cancer, the high expression of NOLC1 was closely related to multiple immune checkpoints, such as LAG3, CTLA-4, and PDCD1LG2, leading to immune tolerance or escape of tumor cells." (PMID 37670166, 2023). "The results revealed LAG3, CD24-SIGLEC10 and HBEGF-CD9 pathways as potential therapeutic targets for dual mutant colorectal cancers." (PMID 36172359, 2022). "Expression of LAG-3, TIM-3 and PD-1 on CD8+ CTL, Th and Treg cells is higher in colorectal cancer liver metastases than in the peritoneal metastases of colorectal cancer." (PMID 36077354, 2022). "This study aimed to investigate the prognostic value of the immune checkpoints TIM‐3, LAG‐3 and PD‐1 in patients with stage I–III colorectal cancer." (PMID 33338327, 2021). "Immunohistochemistry was employed to detect TIM‐3, LAG‐3, PD‐1 and PD‐L1 in 773 patients with stage I–III colorectal cancer." (PMID 33338327, 2021). "Concordant to this, previous research on colorectal cancer found immune checkpoint expression of PD-1, PD-L1, CTLA-4, LAG-3, and IDO as a counterbalancing part of highly inflamed tumors (MSI unstable)." (PMID 33029538, 2020). "In the MC38 colorectal cancer model, ablation of FGL1-LAG-3 interaction with either anti-FGL1 or anti-LAG-3 blocking antibodies inhibits tumor growth." (PMID 30863404, 2019). "In mouse tumor models (Sa1N fibrosarcoma, MC38 colorectal cancer, and MBT-2 bladder cancer), dual blockade of LAG-3 and PD-1 receptors with blocking antibodies has shown to significantly improve the anti-tumor activity than either antibody alone." (PMID 30863404, 2019). "Moreover, PD-1 KO together with LAG-3, TIM-3, TIGIT, and TGFbR2 KO showed improved anti-tumor activity and survival compared to PD-1 alone on a colorectal cancer model." (PMID 41354926, 2025). "Our results warrant future clinical and mechanistic studies to determine whether dMMR/MSI GALNT7-Low colorectal cancers derive greater benefit from PD-1/PD-L1 blockade, alone or in combination with a CTLA-4, TIM-3, or LAG-3 inhibitor." (PMID 40824763, 2025). "Another newly discovered LAG-3 functional ligand, FGL1, is a member of the liver-secreted fibrinogen family of proteins and is highly expressed in a variety of tumor cells, such as melanoma, lung cancer, and colorectal cancer cells." (PMID 38177102, 2024). "In syngeneic mouse models of colorectal cancer (CRC), FS118 enhances the antitumor immune response and decreases the expression of LAG-3 on T cells, which may be due to shedding of LAG-3 from the cell surface to serum." (PMID 36971124, 2023). "This cell state displayed activation (CXCL13) and exhaustion (LAG3, HAVCR2, CD96) markers, which may account for their participation in the immune checkpoint inhibitor sensitivity of MSI-H colorectal cancers." (PMID 35538548, 2022).